TMPRSS4 (transmembrane serine protease 4)
Diseases named in the same sentence as TMPRSS4 in open-access papers (continued):
Sharing a sentence is not in itself a finding about the gene and the disease.
pancreatic cancer (continued). "Clinical characteristics of pancreatic cancer stratified with TMPRSS4 expression." (PMID 33816264, 2021). "TMPRSS4 is overexpressed in pancreatic cancer when compared to healthy tissue." (PMID 28086212, 2017). "Among the nineteen UDEGs, other than the seven UDEGs reported to be carcinogenic and prometastatic genes involved in pancreatic cancer, the other UDEGs, such as ESM1, PCDH7, CORO2A, CEACAM5, GALNT5 and TMPRSS4, are also involved in other cancers." (PMID 40362181, 2025). "TMPRSS4 and ZFP82, have been shown to induce Epithelial-to-Mesenchymal transition (EMT) in pancreatic cancer." (PMID 38902676, 2024). "Overexpressed pancreatic cancer receptors include SLC2A1, MET, IL1RAP, NPR3, GABRP, SLC6A6, and TMPRSS4." (PMID 35359382, 2022). "We identified 7 highly expressed pancreatic cancer cell surface receptors (MET, NPR3, IL1RAP, SLC2A1, SLC6A6, GABRP, and TMPRSS4) in all the analyzed datasets." (PMID 35359382, 2022). "The L5 proteins of 3 serotypes of adenovirus HAdV2, HAdV3, and HAdV5 are docked with the seven highly expressed pancreatic cancer receptors SLC2A1, MET, IL1RAP, NPR3, GABRP, SLC6A6, and TMPRSS4." (PMID 35359382, 2022). "Higher levels of TSPAN1, TMPRSS4, SDR16C5 and CTSE expression were observed in pancreatic cancer than in normal pancreatic tissue (paired t-test, P < 0.0001)." (PMID 33815409, 2021). "TMPRSS4 is a TTSP that has been known to be upregulated in several cancers, particularly in pancreatic and thyroid cancers, and the expression of TMPRSS4 has been correlated with the metastatic potential of pancreatic cancer." (PMID 23922976, 2013). "Furthermore, we showed that TMPRSS4 might promote cell proliferation and inhibit apoptosis through activating ERK1/2 signaling pathway in pancreatic cancer cells." (PMID 33816264, 2021). "Consistent with this, analysis of TCGA datasets revealed that TMPRSS4 DNA is hypomethylated in certain cancer types, including NSCLC and pancreatic cancer, but not in colorectal or gastric cancers (Kim, unpublished results)." (PMID 37009799, 2023).
colon carcinoma (12 papers, 2011 to 2025). "TMPRSS4 is an important mediator of cell migration, invasion, epithelial–mesenchymal transition and metastasis in colon cancer cells, and increased TMPRSS4 expression correlated with colorectal cancer stage progression." (PMID 40362181, 2025). "TMPRSS4 also activates NF-κB in lung, prostate, and colon cancer cells, possibly through FAK- or AXL-mediated activation of AKT64,69." (PMID 37009799, 2023). "Previously, we screened a small molecule compound library and identified novel 2-hydroxydiarylamide derivatives that inhibit TMPRSS4 serine protease activity and suppress invasion of colon cancer cells." (PMID 31292507, 2019). "We also investigated the anti-tumor activity of KRT1853 and IMD-0354 in nude mice bearing endogenous TMPRSS4-expressing HCT116 colon cancer xenografts." (PMID 31292507, 2019). "Previously, we reported that novel 2-hydroxydiarylamide derivatives inhibited TMPRSS4 serine protease activity and efficiently suppressed invasion of colon cancer cells overexpressing TMPRSS414." (PMID 31292507, 2019). "These derivatives show promising anti-invasive activity of colon cancer cells overexpressing TMPRSS4." (PMID 29258163, 2017). "Overexpression of TMPRSS4 leads to a significant increase in both in vitro invasion and in vivo metastasis of colon cancer cells." (PMID 29258163, 2017). "Recent studies in thyroid, pancreatic and colon carcinoma showed that TMPRSS4 has a protumorigenic and metastatic role in these tumour types." (PMID 22067904, 2011). "Metastatic implications of TMPRSS4 have been studied in colon cancer, which prompted us to analyse cell migration and metastasis in vivo." (PMID 22067904, 2011). "TMPRSS4 induces epithelial-to-mesenchymal transition and promotes metastasis in colon cancer cells." (PMID 38409471, 2024). "TMPRSS4 confers stem-like properties on prostate and colon cancer cells, inducing aldehyde dehydrogenase (ALDH) activation, tumorsphere formation, and resistance to chemotherapeutics and anoikis, thereby increasing the survival of circulating tumor cells and promoting early metastasis." (PMID 37009799, 2023). "Reduction of TMPRSS4 expression in lung and prostate cancer cells inhibits tumor growth and metastasis in xenograft nude mouse models, while overexpression of TMPRSS4 in lung, prostate, and colon cancer cells promotes tumor growth and metastasis in vivo." (PMID 37009799, 2023). "Previous reports suggest that TMPRSS4 might assist the cellular proliferation, progression, and invasion in lung and colon cancer cells by activating the ERK1/2 and p38 MAPK signaling pathways." (PMID 33816264, 2021). "TMPRSS4, initially referred to as TMPRSS3, is highly overexpressed in various cancers and is associated with poor prognosis in non-small-cell lung cancer, triple-negative breast cancer, cervical cancer, gastric cancer, and colon cancer patients." (PMID 27385093, 2016). "Moreover, the overexpression of TMPRSS4 in colon cancer cells was shown to promote epithelial–mesenchymal transition (EMT) through the upregulation of integrin α5, thereby enhancing motility and invasiveness." (PMID 22067904, 2011). "Elevated TMPRSS4 expression is associated with poor prognosis in non-small cell lung cancer with squamous cell histology, triple-negative breast cancer, cervical cancer, gastric cancer, colon cancer, and prostate cancer patients." (PMID 31292507, 2019). "TMPRSS4 modulated both invasion and proliferation via Slug and cyclin D1 Increased TMPRSS4 was responsible for invasion largely through an intracellular signaling cascade that activates FAK, ERK1/2, Akt, Src, and Rac1 in colon cancer." (PMID 36380313, 2022). "We previously reported that TMPRSS4 induces the invasion and EMT of colon cancer cells via upregulation of integrin α5." (PMID 27385093, 2016). "The TMPRSS4 downregulates epithelial markers, such as E-cadherin and P-cadherin, and upregulates mesenchymal markers that induce EMT in colon cancer cells." (PMID 22067904, 2011).
colon carcinoma (continued). "Similarly, suppression of endogenous TMPRSS4 reduced ALDH activity in HT-29 and HCT-116 colon cancer cells, and this was accompanied by downregulation of SLUG, TWIST1, and SOX2, but not BMI1 or CD133." (PMID 34809669, 2021).
colorectal cancer (12 papers, 2013 to 2025). A primary or metastatic malignant neoplasm that affects the colon or rectum. "Previously, we reported that TMPRSS4 plays important roles in tumor cell migration, invasion, and metastasis, and that enhanced expression of TMPRSS4 is associated with colorectal cancer stage progression." (PMID 31292507, 2019). "Previously, we reported that TMPRSS4 plays important roles in migration, invasion, and metastasis of human epithelial cancer cells, and that elevated expression of TMPRSS4 is associated with stage progression of colorectal cancer." (PMID 34809669, 2021). "Consistent with this, expression of TMPRSS4 in human colorectal cancer tissues correlates positively with enhanced expression of integrin α5 and negatively with expression of E-cadherin, thereby confirming TMPRSS4-mediated regulation of EMT46." (PMID 37009799, 2023). "A high level of transmembrane serine protease 4 (TMPRSS4) is associated with the poor prognosis of patients with non-small cell lung cancer (NSCLC), gastric cancer, colorectal cancer, prostate cancer, and other cancers." (PMID 36076996, 2022). "Taken together, these observations indicate that TRIM31 gene expression is positively correlated with TMPRSS2 and TMPRSS4 in GI cell lines, solid tumors and colorectal cancer PDOs." (PMID 35970857, 2022). "We performed the analysis in Oncomine databases and found that TMPRSS4 was significantly upregulated in breast cancer, cervical cancer, colorectal cancer, gastric cancer, and ovarian cancer but downregulated in brain and CNS cancer." (PMID 36380313, 2022). "In colorectal cancer, the high expression state of TMPRSS4 is significantly correlated with advanced TNM stage and predicted poor prognosis." (PMID 32695668, 2020). "Elevated expression of transmembrane serine protease 4 (TMPRSS4) correlates with poor prognosis in non-small cell lung cancer, gastric cancer, colorectal cancer, prostate cancer, and other cancer patients." (PMID 31292507, 2019). "We previously reported that TMPRSS4 is an important mediator of the migration, invasion, and metastasis of human epithelial cancer cells, and increased TMPRSS4 expression correlates with colorectal cancer stage progression." (PMID 27385093, 2016). "TMPRSS4 predicted the unfavorable prognosis of stage III-IV colorectal cancer and ESCC." (PMID 36380313, 2022). "Importantly, higher co-expression of TMPRSS2 and TMPRSS4 relative to normal was also observed in a human gastrointestinal cancer cell line dataset and colorectal cancer organoids." (PMID 35970857, 2022). "Transmembrane protease, serine 4(TMPRSS4) is a TTSP that is highly expressed in pancreatic, thyroid, lung and colorectal cancers." (PMID 23922976, 2013). "TMPRSS4, a protease of the Type II transmembrane serine protease (TTSP) family, is highly expressed in pancreatic, thyroid, lung, gastric, cervical, breast, and colorectal cancer tissues and directly correlates with poor outcome." (PMID 26993610, 2016).
thyroid cancer (12 papers, 2012 to 2022). "In thyroid cancer, TMPRSS4 is detected to be significantly associated with the promotion of proliferation in thyroid cancer cells." (PMID 32695668, 2020). "Overexpression of TMPRSS4, a cell surface-associated transmembrane serine protease, has been reported in pancreatic, colorectal and thyroid cancers, and has been implicated in tumor cell migration and metastasis." (PMID 22692880, 2012). "Consistent with our findings, a recent paper reported that TMPRSS4 promotes thyroid cancer proliferation via CREB phosphorylation." (PMID 27385093, 2016). "Since the cloning of the human TMPRSS4 gene, several studies have reported high expression of TMPRSS4 at the transcriptional level in pancreatic, colorectal, and thyroid cancers via Northern blot analyses, microarray gene-chips, and RT-PCR." (PMID 22692880, 2012). "Similarly, a recent paper showed that TMPRSS4 promotes thyroid cancer cell proliferation via CREB phosphorylation." (PMID 31292507, 2019). "TMPRSS4 has been reported to stimulate proliferation in prostate and thyroid cancer cells." (PMID 31659178, 2019). "Therefore, the association between VDR to ECM1 and TMPRSS4, suggested a potential role of VDR in thyroid carcinoma." (PMID 28092021, 2017). "Additional in vitro studies demonstrated that 25(OH)D3 was able to decrease proliferative activity of follicular thyroid cells and modulate expression of ECM protein-1 (ECM1) and the type II transmembrane serine protease-4 (TMPRSS4), two independent predictor of thyroid carcinoma." (PMID 28092021, 2017). "To date, TMPRSS4 and immune infiltration in thyroid carcinoma (TC) are largely unknown." (PMID 36380313, 2022). "Similarly, TMPRSS4 facilitates cellular proliferation via CREB phosphorylation in thyroid cancer." (PMID 33816264, 2021). "Transmembrane protease serine 4 (TMPRSS4) is a type II transmembrane serine protease overexpressed in several cancer types, including gastric, breast, lung and thyroid cancers." (PMID 30089490, 2018).
gastric cancer (11 papers, 2013 to 2023). A primary or metastatic malignant neoplasm involving the stomach. "In contrast, overexpression of TMPRSS4 is associated with stage progression and metastasis of colorectal and gastric cancers." (PMID 37009799, 2023). "The study revealed that the expression of TMPRSS4 in gastric cancer lesions were closely associated with the age, size of tumor, location of tumor, depth of invasion, vessel invasion, lymph node and distant metastasis and TNM stage." (PMID 23922976, 2013). "miR-551b-3p, the expression of which is inhibited by lncRNA SMARCC2, functions as a tumor suppressor by directly suppressing TMPRSS4 expression, as well as the proliferation, motility and invasiveness of gastric cancer cells." (PMID 37009799, 2023). "Elevated TMPRSS4 enhanced the invasive ability of gastric cancer cells through activation of NF-κB and induction of MMP-9 expression." (PMID 36380313, 2022). "In gastric cancer, upregulation of TMPRSS4 facilitates cell migration and invasion through the activation of NF-κB/MMP-9 signaling." (PMID 32695668, 2020). "The expression of TMPRSS4 was found to significantly correlate with the prognosis of gastric cancer." (PMID 23922976, 2013). "Further multivariate analysis suggested that the depth of invasion, lymph node and distant metastasis, TNM stage, and up-regulation of TMPRSS4 were independent prognostic indicators for gastric cancer." (PMID 23922976, 2013). "We further examined TMPRSS4 expression in gastric cancer specimens and its correlation with Erk1 expression." (PMID 23922976, 2013). "Two hundred and four gastric cancer cases had low expression of both TMPRSS4 and Erk1, and one hundred and forty-four gastric cancer cases had high expression of both TMPRSS4 and Erk1." (PMID 23922976, 2013). "TMPRSS4 protein was detected in 245 of 436 (56.19%) cases of human gastric cancer, high expression of TMPRSS4 protein was detected in 203 (46.56%) tumors." (PMID 23922976, 2013). "The present study investigated the clinical significance of transmembrane protease, serine 4(TMPRSS4) and extracellular signal-regulated kinases 1 (Erk1) in the development, progression and metastasis of gastric cancer." (PMID 23922976, 2013). "Overexpression of TMPRSS4 is associated with stage progression and metastasis of multiple cancers, including colorectal and gastric cancers (Kim, unpublished results), suggesting a potential role for TMPRSS4 in the progression of noninvasive tumors to invasive malignancies." (PMID 37009799, 2023). "We found a positive correlation between TMPRSS4 and Erk1 expression, suggesting that TMPRSS4 may be involved in the carcinogenesis, progression and metastasis of gastric cancer through promotion of cell proliferation by Erk1 activation." (PMID 23922976, 2013). "Correlation between TMPRSS4 expression and clinicopathological features of gastric cancer." (PMID 23922976, 2013). "TMPRSS4 and Erk1 proteins could be useful markers to predict tumor progression and prognosis of gastric cancer." (PMID 23922976, 2013). "Expression of TMPRSS4 in gastric cancer is significantly associated with lymph node and distant metastasis, high Erk1 expression, and poor prognosis." (PMID 23922976, 2013). "Immunohistochemistry was employed to analyze TMPRSS4 and Erk1 expression in 436 gastric cancer cases and 92 non-cancerous human gastric tissues." (PMID 23922976, 2013). "Protein levels of TMPRSS4 and Erk1 were up-regulated in gastric cancer lesions compared with adjacent noncancerous tissues." (PMID 23922976, 2013). "The biological functions and clinical significance of TMPRSS4 and Erk1 in gastric cancer are not understood." (PMID 23922976, 2013).
prostate carcinoma (11 papers, 2016 to 2024). A carcinoma that arises from epithelial cells of the prostate gland. "Here, we investigated whether TMPRSS4 confers cancer stem–like properties to prostate cancer cells and characterized the underlying mechanisms." (PMID 34809669, 2021). "Recent studies show that blocking TMPRSS4 activity reduced cell migration and invasion, and inhibited tumour growth in lung and prostate cancer." (PMID 37009799, 2023). "TMPRSS4 accelerated tumor invasion by promoting uPA gene expression or transferring pro-uPA into its active form in lung and prostate cancer.TMPRSS4 can promote HCC proliferation, invasion, and angiogenesis by regulating HB-EGF." (PMID 36380313, 2022). "We also showed that TMPRSS4 promotes invasion and proliferation of lung and prostate cancer cells through transcription factors AP-1 and SP1 in a manner dependent on MAPKs." (PMID 34809669, 2021). "In this study, we report that TMPRSS4 confers stem–like properties to prostate cancer cells, mainly through upregulation of SLUG, TWIST1, and SOX2, leading to CTC survival and thereby contributing to metastasis as well as tumorigenicity." (PMID 34809669, 2021). "In particular, we postulated that TMPRSS4 contributes to the malignancy of prostate cancer via its tumor-initiation capacity." (PMID 34809669, 2021). "In summary, TMPRSS4 gives prostate cancer cells cancer stem–like features, including ALDH activation, tumorsphere formation, and resistance to anoikis and drugs, thereby contributing to tumor growth and metastatic seeding." (PMID 34809669, 2021). "Together, these findings suggest that TMPRSS4 promotes CSC features in prostate cancer through upregulation of the SLUG- and TWIST1-induced stem cell factor SOX2 beyond EMT." (PMID 34809669, 2021). "Elevated expression of TMPRSS4 in various types of cancer, including pancreatic, thyroid, lung, colon, and prostate cancers, is correlated with poor prognosis." (PMID 34809669, 2021). "Previously, we demonstrated that TMPRSS4 promotes invasion and proliferation of prostate cancer cells." (PMID 34809669, 2021). "In previous work, we observed that high expression of TMPRSS4 in prostate cancer patients was significantly correlated with reduced disease-free survival." (PMID 34809669, 2021). "We also analyzed aldehyde dehydrogenase (ALDH) activity in TMPRSS4-overexpressing cells, as elevated ALDH activity is associated with CSC features and poor prognosis in several cancers, including prostate cancer." (PMID 34809669, 2021). "A recent study suggests that TMPRSS4 regulates both proliferation and invasion through Slug and cyclin D1 in prostate cancer cells." (PMID 33816264, 2021). "Previously, we reported that TMPRSS4 promotes prostate cancer cell invasion and proliferation through activation of Sp1 and AP-1 transcription factors and subsequent upregulation of Slug and cyclin D111,15." (PMID 31292507, 2019). "Together, these results suggest that TMPRSS4 induces prostate cancer cell proliferation through upregulation of cyclin D1." (PMID 27385093, 2016). "In this study, we found that TMPRSS4 induced AP-1 activation and subsequent expression of Slug and cyclin D1, leading to prostate cancer cell invasion and proliferation." (PMID 27385093, 2016). "Taken together, these results suggest that TMPRSS4 induces AP-1 activation and subsequent induction of Slug and cyclin D1, leading to prostate cancer cell invasion and proliferation." (PMID 27385093, 2016). "Because tumorigenicity reflects tumor-initiating capacity, we investigated whether TMPRSS4 in prostate cancer cells promotes characteristic traits of tumor-initiating/cancer stem cells." (PMID 34809669, 2021). "First, we characterized stable TMPRSS4-overexpressing PC3 prostate cancer cell lines." (PMID 34809669, 2021). "In prostate cancer cells, overexpressed TMPRSS4 promotes migration via the progression of EMT." (PMID 32695668, 2020).